RNU6-479P (RNA, U6 small nuclear 479, pseudogene)
Gene: Small nuclear RNA gene on chromosome 4 (183,653,572 to 183,653,676, reverse strand). Ensembl gene ENSG00000252157.
Homologues: Orthologues: chimpanzee U6 (98% identical), macaque U6 (94% identical), dog U6 (63% identical). Paralogues in human: RNU6-1011P (71% identical), RNU6-166P (69% identical), RNU6-38P (69% identical), RNU6-41P (69% identical), RNU6-48P (69% identical), RNU6-996P (69% identical), RNU6-1060P (68% identical), RNU6-1075P (68% identical), RNU6-1303P (68% identical), RNU6-187P (68% identical), RNU6-29P (68% identical), RNU6-338P (68% identical), and 1281 more.